IL15 (interleukin 15)
Diseases named in the same sentence as IL15 in open-access papers (continued):
Sharing a sentence is not in itself a finding about the gene and the disease.
breast carcinoma (continued). "Combined injection of IL-7 and IL-15 into breast cancer lesions after radiofrequency thermal ablation (RFA) can reduce the number of MDSCs, and inhibit the growth and metastasis of breast cancer." (PMID 27542274, 2016). "Through a combination of RNA sequencing analysis, database screening and invasion assays we identified IL7/IL7R and IL15/IL15R as pairs of chemokines and receptors with potential roles in promoting chemotactic migration of breast cancer cells with mesenchymal properties towards the lymphatics." (PMID 38055067, 2023). "IL15 is important for T and NK cell activity a mechanisms that our CD169+ Mo-M did not have in vitro, and for antitumor immunity which does not support our prognostic data regarding CD169+ TAMs in primary breast cancers." (PMID 37404831, 2023). "Within this study we analyzed the distribution of IL-15 and eotaxin concentrations and reveal the differences in their expression in the sera of breast cancer patients with and without circulating tumor cells." (PMID 32929618, 2021). "Meanwhile, LSM4 was also correlated with “Immune response IL-15 signaling via MAPK and PI3K cascade”, “Cell cycle spindle assembly and chromosome separation”, and “Mitogenic action of ErbB2 in breast cancer”, which are immune- and cell cycle-related pathways that play roles in BRCA growth." (PMID 34638387, 2021). "CLEC2B, HLA-E, IL15, and VIM all appear in the 4 subtypes at the same time, which may mean that they play a more general role in different subtypes of breast cancer." (PMID 33304391, 2020). "Mice knocked out for IL-15 and transgenic for HER2/neu oncogene (IL15KO/NeuT mice) developed mammary carcinomas with a median latency of 16 weeks, significantly shorter than the median latency of 20 weeks displayed by HER2/neu transgenic mice with wild-type IL-15 (NeuT mice)." (PMID 25997501, 2015). "To examine the role of IL-15 in a more relevant model we utilized an immunologically tolerant mouse model of spontaneous mammary tumor formation (MT) and examined tumor formation in the absence of IL-15 (IL-15 KO/MT) or with IL-15 overexpression (IL-15 TG/MT)." (PMID 25879689, 2015). "Our findings indicate that while a single dose of IL-15 complexes administered intratumorally is insufficient in producing a significant change to anti-PD-1 immunotherapy, a second dose generates an increase in anti-tumoral immune markers in murine EO771 breast cancer as well as increased survival." (PMID 41373645, 2025). "On the other hand, a recent study carried out using the tumor tissues of 148 patients with primary breast cancer correlated the high levels of PD-L1 with low circulating values of vascular endothelial growth factor (VEGF), tumor necrosis factor-beta (TNF-β), and interleukin 15 (IL-15)." (PMID 37834467, 2023). "Serum IL-15, simply measured in the everyday clinical routine, could therefore be an independent prognostic marker of major importance in terms of DFS and OS for breast cancer patients." (PMID 32929618, 2021). "In spite of wide infection ability of adenovirus type 5 on tumor cells and normal non-malignant cells, MTT and in vivo assays showed that SG400-E2F/IL-15 and SG400-E2F both could selectively infect and kill breast cancer cells; and SG400-E2F/IL15 exhibited highest cytocidal effects on tumor cells." (PMID 31278126, 2019). "However, IL-15 has not been applied on breast cancer gene therapy in spite of its high potential anti-tumor property." (PMID 31278126, 2019). "In addition, there is a lack of studies that have examined the impact of IL-15 on solid epithelial tumors such as breast cancer." (PMID 25879689, 2015). "Previous in vitro and in vivo studies have shown that cytokines such as IL-2, IL-12, IL-15 and interferon can enhance the effect of antibody-ADCC for immunotherapy of cancer, e.g., IL-2 and IL-15 enhanced NK cell response to Herceptin-coated Her2/neu+ breast cancer cells in vitro." (PMID 20939894, 2010).
breast carcinoma (continued). "Furthermore, incorporating cytokine receptors such as IL‐15 or IL‐7 receptors or proinflammatory cytokines into CAR‐based immune cell constructs can be used to reprogram the immunosuppressive TME and extend the survival of CAR‐T and CAR‐NK cells in the hostile TME of breast cancer." (PMID 35762299, 2022). "Moreover, this novel oncolytic virus selectively kills tumor cells and simultaneously releases IL-15, as well as enhancing the inhibitory effect on breast cancer, even on triple negative breast cancer which tests negative for estrogen receptors, progesterone receptors, and excess HER2 protein." (PMID 31278126, 2019).
rheumatoid arthritis (69 papers, 2006 to 2025). A chronic, systemic autoimmune disorder characterized by inflammation in the synovial membranes and articular surfaces. "IL-15 has also been linked with pain in various rheumatologic diseases including rheumatoid arthritis (RA), lupus, and OA." (PMID 32793194, 2020). "Functionally, IL-15 has been implicated in the pathogenesis of chronic inflammatory disorders including psoriasis, rheumatoid arthritis, and celiac disease." (PMID 27610005, 2016). "IL-15 is a proinflammatory cytokine associated with several autoimmune diseases, particularly rheumatoid arthritis." (PMID 22888423, 2012). "IL-7 is known to have an important role in the development of rheumatoid arthritis, while IL-15 has been associated with the development of joint inflammation." (PMID 19156204, 2009). "However, IL-15 gene variants have been associated with several autoimmune disorders, including psoriasis, type 1 diabetes, ulcerative colitis, and rheumatoid arthritis." (PMID 40266334, 2025). "IL-15 has been implicated in the pathogenesis of various autoimmune conditions such as coeliac disease (CD), type 1 diabetes, rheumatoid arthritis (RA), psoriasis, multiple sclerosis (MS), vitiligo, systemic lupus erythematosus (SLE), and inflammatory bowel diseases (IBD)." (PMID 38405398, 2024). "Octreotide (OCT)—which is a first-generation SSA—modulates cytokine production in rheumatoid arthritis synoviocytes through interleukin-15 and TNF-α inhibition and increases interleukin-10 levels." (PMID 40732232, 2025). "Although current research is largely limited to preclinical studies and animal models, the encouraging outcomes in other autoimmune diseases—such as rheumatoid arthritis and cancer—highlight the translational potential of IL-15-targeted strategies." (PMID 40791580, 2025). "Inflammatory bowel disease, autoimmune diabetes, rheumatoid arthritis, and celiac disease are examples of chronic inflammation and tissue-specific autoimmune diseases based on the IL-15 mechanism." (PMID 39507777, 2024). "The function of IL15 in rheumatoid arthritis, which correlates with autoantibody activity, is also well-documented." (PMID 38728237, 2024). "It is well known that lymphocytes development are enhanced by the action of interleukin-15 (IL-15) which has a role in certain diseases such as rheumatoid arthritis and multiple sclerosis that have an autoimmune etiology." (PMID 37206670, 2023). "Overexpression of IL-15 has been shown to be involved in several autoimmune disorders including rheumatoid arthritis (RA), psoriasis, inflammatory bowel diseases, celiac disease, lupus, vitiligo, alopecia areata, and multiple sclerosis." (PMID 35592318, 2022). "However, IL-15 overexpression has been associated with the pathogenesis and development of several autoimmune diseases, including rheumatoid arthritis (RA), ulcerative colitis, systemic lupus erythematosus and multiple sclerosis." (PMID 34922462, 2021). "In rheumatoid arthritis, IL-15 promoted the HUVEC tube formation which contributed to the disease progression." (PMID 33557944, 2021). "The revealed decrease in Treg proliferation under IL-7 and IL-15 exposure can lead to a delay in Treg pool reconstitution in patients with rheumatoid arthritis in the case of lymphopenia." (PMID 33809452, 2021). "But some studies have found the proinflammatory effect of IL‐15 in some diseases, such as multiple sclerosis, inflammatory bowel disease and rheumatoid arthritis." (PMID 34586716, 2021). "The effect of IL-7 on CD28null T cells has not been previously studied in any disease, while the effect of IL-15 on CD28null T cells has been investigated in multiple sclerosis, elderly individuals, and rheumatoid arthritis." (PMID 32647892, 2021). "Much evidence demonstrated that IL-15 can boost immune cells to exacerbate disease progression such as rheumatoid arthritis and stroke." (PMID 29616032, 2018).
rheumatoid arthritis (continued). "In the periphery, studies have demonstrated that IL-15 contributes to the immunopathology of several inflammatory diseases, such as rheumatoid arthritis and inflammatory bowel disease." (PMID 29616032, 2018). "In patients with rheumatoid arthritis, IL-15 is detected at high concentrations in synovial fluid, and genetic variants of IL-15 associate with progression of joint destruction in Caucasian but not Japanese patients." (PMID 29440371, 2018). "Interleukin (IL)-15, one of the members of this protein family, is a pro-inflammatory cytokine that is overexpressed in several inflammatory disorders such as Rheumatoid Arthritis (RA), psoriasis, ulcerative colitis and sarcoidosis." (PMID 27671547, 2016). "Humax-IL15, a human IgG1 anti-IL-15 monoclonal antibody, has been shown to improve symptoms in patients with rheumatoid arthritis." (PMID 27847409, 2016). "An increase of IL-15 protein in the intestinal mucosa and synovial cavity of celiac disease and rheumatoid arthritis patients, respectively, stimulates dendritic cells, NK cells, and effector T cells to exacerbate the disease." (PMID 26417430, 2015). "The role of interleukin (IL)-15 in the pathogenesis of rheumatoid arthritis (RA) is well established; however, systemic knockdown of IL-15 receptor (IL-15R) for reduction in inflammation at local sites has not been demonstrated." (PMID 24223832, 2013). "It has been reported that IL-15 is produced excessively in the joints of rheumatoid arthritis (RA) patients and induces recruitment of T cells to arthritic joints and activates T cells to induce tumor necrosis factor (TNF)-α production." (PMID 24366113, 2013). "Interleukin (IL)-15 and IL-17 are thought to play an important role in the pathogenesis of rheumatoid arthritis (RA) because both pro-inflammatory cytokines are found in synovial fluid of RA patients." (PMID 24366113, 2013). "IL-15 is associated with autoimmune and inflammatory diseases and was recently shown to be upregulated in T cell-mediated inflammatory disorders, such as rheumatoid arthritis (RA) and inflammatory bowel diseases." (PMID 22876248, 2012). "IL-15 is present at high concentrations in rheumatoid arthritis synovial fluid and elevated in the serum of patients with systemic lupus erythematosus or type 1 diabetes." (PMID 23028916, 2012). "IL-15 had been found to determine the activation level of macrophages in mouse rheumatoid arthritis model." (PMID 23028657, 2012). "Fifth, our data show that dermal fibroblasts in psoriasis are strongly positive for Wnt5a and activated fibroblasts from rheumatoid arthritis are synthesize inflammatory cytokines, most notably IL15, subsequent to Wnt5a/Fzd5 signalling." (PMID 19399181, 2009). "The therapeutic benefit achieved by inhibiting IL-15 is supported by evidence that HuMax-IL-15, a fully human anti-IL-15 mAb, produced encouraging signs of efficacy in rheumatoid arthritis patients." (PMID 18234077, 2008). "Such a mechanism is supported by the observation that IL-15 can prevent TNFα-induced apoptosis of synovial fibroblasts in rheumatoid arthritis." (PMID 17784951, 2007). "IL-15 has emerged as an important molecule involved in autoimmunity and transplantation, and is considered a possible target for therapy in rheumatoid arthritis." (PMID 17784951, 2007). "Moreover, a recent study conducted on rheumatoid arthritis synoviocytes showed that octreotide suppresses production of interleukin (IL)‐15 and increases IL‐10,30 both components of the immune pituitary adenoma TME." (PMID 40789673, 2025). "Additionally, similar to other forms of rheumatoid nodules, higher levels of IL-1, together with IL-12, IL-18, IL-15, and IL-10, have been reported in pulmonary rheumatoid nodules." (PMID 37238933, 2023). "IL-15 overexpression has been observed in human and murine model of rheumatoid arthritis." (PMID 35592318, 2022).
rheumatoid arthritis (continued). "Meanwhile, IL-15 could regulate tissue-resident T cells and limit tissue destruction, while chronically dysregulated IL-15 also promotes organ-specific autoimmune diseases including rheumatoid arthritis, multiple sclerosis, type 1 diabetes and celiac disease." (PMID 36320075, 2022). "Nevertheless, dysregulation of IL-15 expression with concomitant elevated levels of IL-15 has been reported in several autoimmune diseases, including rheumatoid arthritis, psoriasis, lupus, sarcoidosis, type 1 diabetes, celiac disease, and inflammatory bowel diseases." (PMID 35592318, 2022). "The role of IL-15 in autoimmune disease comes extensively from studies of rheumatoid arthritis." (PMID 35747794, 2022). "In addition, in CHIP carriers, pathways such as IL-15 signaling, B cell receptor signaling, lupus in B cells signaling, and rheumatoid arthritis pathways were dysregulated in comparison to control." (PMID 36437309, 2022). "IL-15,a proinflammatory cytokine that promotes activation of T-cells, neutrophils, and macrophages, is expressed in several inflammatory disorders, including rheumatoid arthritis, psoriasis, and autoimmune diabetes." (PMID 33946446, 2021). "Although IL-15-activated NK cells from the synovial fluid of rheumatoid arthritis patients efficiently induced osteoclast formation from autologous monocytes, IL-15-activated NK cells from healthy donors triggered osteoclast apoptosis, thus displaying an anti-osteoclastogenic effect." (PMID 29440371, 2018). "In the context of rheumatoid arthritis, IL-15 drives the development and proliferation of Th17 cells in a mechanism that may involve IL-12 as an intermediary." (PMID 27610005, 2016). "IL-15 has been reported to be involved in a number of autoimmune diseases, including rheumatoid arthritis, inflammatory bowel disease, and multiple sclerosis, in which IL-15 promotes the effector function of cytotoxic CD8+ T cells to destroy the target tissues." (PMID 26417430, 2015). "Evidence is emerging for the importance of IL-15 in the pathogenesis of rheumatoid arthritis." (PMID 18234077, 2008). "IL-15 should be considered a putative target for treatment of SSc, perhaps using an anti-human IL-15 antibody that is under development in a clinical phase II trial for the treatment of rheumatoid arthritis." (PMID 17784951, 2007). "Excessive JAK/STAT stimulation by cytokines such as IL-1, IL-6, IL-15, TNF-α, and IFN has been associated with rheumatoid arthritis (RA), multiple sclerosis, inflammatory bowel disease, and periodontal disease, to name a few." (PMID 37373437, 2023). "Other cytokines that are deregulated in chronic inflammatory diseases (e.g. rheumatoid arthritis, RA) and are currently targeted in patients are IL-7 and IL-15 that belong to the common gamma chain cytokine family." (PMID 32647892, 2021). "In addition, IL-15-activated NK cells from synovial fluid obtained from patients with rheumatoid arthritis could efficiently induce the formation of osteoclasts from monocytes." (PMID 29440371, 2018). "Interleukin-15 is an immunostimulatory cytokine overexpressed in several autoimmune and inflammatory diseases such as Rheumatoid Arthritis, psoriasis and ulcerative colitis; thus, inhibition of IL-15-induced signaling could be clinically beneficial in these disorders." (PMID 27671547, 2016). "IL-15 and IP-10, in conjunction with CYCLOSPORINE, have been identified as significant inflammatory biomarkers in rheumatoid arthritis." (PMID 38376769, 2024). "IL-22 in pathological conditions such as rheumatoid arthritis by upregulating RANKL expression and IL-15 synergistically enhancing RANKL induced osteoclast differentiation." (PMID 36151243, 2022). "Thus, elevated levels of IL-7 and IL-15 in synovia, along with elevated levels of inflammatory cytokines, may have additional negative effects on the functional activity of Treg cells in rheumatoid arthritis." (PMID 33809452, 2021).
rheumatoid arthritis (continued). "NKG2D+ CD4+ T cells were initially found on peripheral blood and synovial fluid from rheumatoid arthritis (RA) patients, putatively as result of increased TNF-α and IL-15 levels in this disease." (PMID 29740438, 2018). "In rheumatoid arthritis, the substantial amount of soluble MIC released by synoviocytes failed to downregulate NKG2D on CD4+ T cells, possibly due to high levels of IL-15 and TNF-α." (PMID 30150983, 2018). "Excess IL-15 expression on monocytes leads to increased MHC II expression, contributing to activation or proliferation of T cells in diseases such as rheumatoid arthritis." (PMID 22363505, 2012). "Wnt5a is also upregulated in synovial fibroblasts of inflammatory joints in rheumatoid arthritis where it induces IL6, IL8, and IL15." (PMID 19399181, 2009). "Moreover, high levels of inflammatory/arthrogenic factors, including cytokines (TNF-α, IL-6, IL-7, IL-15, and BAFF) and chemokines (CCL-2, CCL-5, and CXCL-10) have been reported in the serum and/or synovia of rheumatoid arthritis patients." (PMID 38720890, 2024). "NK cells interact with fibroblast-like synoviocytes (FLS), leading to proinflammatory responses with increased IL-15 expression by FLS followed by the production of proinflammatory chemokines, cytokines, and matrix metalloproteinases (MMPs) in SpA and rheumatoid arthritis (RA) patients." (PMID 28812990, 2017). "In patients with OA, the immunoexpression levels of TNF-α, IL-1β, IL-7, MMP-1, MMP-2, and MMP-3 were significantly higher in patients with active rheumatoid arthritis (RA), whereas the immunoexpression levels of IL-1, IL-2, IL-4, IL-6, IL-15, IL-18, and MMP-3 were not statistically different." (PMID 40004793, 2025). "Such high doses of IL-15 might in fact reflect severe pathological conditions, such as in the case of the highly inflammatory synovium of patients with rheumatoid arthritis, inducing T cell proliferation in the absence of concomitant TCR signals." (PMID 23028916, 2012). "In patients with rheumatoid arthritis, soluble MICA failed to downregulate NKG2D on CD4+ T cells and CD8+ T cells, possibly due to counteractions of IL-15 and TNF-α." (PMID 30150983, 2018).